RNU6-892P (RNA, U6 small nuclear 892, pseudogene)
Gene: Small nuclear RNA gene on chromosome 8 (20,229,779 to 20,229,877, forward strand). Ensembl gene ENSG00000222267.
Homologues: Orthologues: chimpanzee U6 (99% identical), macaque U6 (83% identical), pig U6 (79% identical). Paralogues in human: RNU6-1084P (84% identical), RNU6-944P (83% identical), RNU6-950P (83% identical), RNU6-1060P (82% identical), RNU6-1243P (82% identical), RNU6-1287P (82% identical), RNU6-214P (82% identical), RNU6-445P (82% identical), RNU6-571P (82% identical), RNU6-657P (82% identical), RNU6-698P (82% identical), RNU6-727P (82% identical), and 1289 more.